CD47 (CD47 molecule)
Diseases named in the same sentence as CD47 in open-access papers (continued):
Sharing a sentence is not in itself a finding about the gene and the disease.
tumor (continued). "Therefore, targeting CD47 has promising therapeutic potential and KAIMRC1 cell line may be used as a model to study CD47 mediated tumor invasion." (PMID 29187162, 2017). "CD47 is expressed on normal (non-tumor) cells at varying levels, but highly on tumor cells." (PMID 28484448, 2017). "Interestingly, blocking the interaction of CD47 on cancer cells and its corresponding receptor SIRPα on macrophages results in efficient PrCR of tumor cells but not of normal cells both in vitro and in vivo." (PMID 27785369, 2016). "Through its original mechanism of action which supposes concomitant disruption of TSP-1:CD47 interaction and enhancement of CD36 activation by TSP-1, TAX2 may inhibit tumor progression while limiting many of the undesired side effects of broadly inhibiting important physiological functions of CD47." (PMID 26578962, 2015). "Inhibition of the CD47-SIPRα interaction has been demonstrated to be an attractive strategy to increase the phagocytic activity of an anti-CD20 mAb, whereby phagocytosis was significantly increased by the co-injection of an anti-CD47 mAb, leading to complete tumour eradication." (PMID 25672245, 2015). "The only situation where nonactivated T or B cells have been found to undergo CD47-induced apoptosis is when immobilized anti-CD47 mAb has been used, but not when using soluble CD47 ligands or mAbs known to induce apoptosis in activated cells or tumor cells." (PMID 23401787, 2013). "While ITGB1 and CD47 may not show strong differential expression between tumor and adjacent tissues, their functional role in tumor invasion, immune evasion, and metastatic competence has been repeatedly demonstrated, supporting them as functional rather than diagnostic targets." (PMID 41596257, 2026). "Moreover, within the αvβ3+/CD47+ tumor cells, αvβ3+ green fluorescence and CD47+ red fluorescence were evenly distributed around the nucleus (DAPI+ blue) with clear overlap, demonstrating a clear correlation between the expression of αvβ3 and CD47 in the patient's tumor cells." (PMID 41168993, 2026). "Chemotherapy can remodel the tumor microenvironment and may lead to downregulation of CD47 expression, thereby potentially suppressing the “do not eat me” signal and enhancing macrophage-mediated phagocytosis of tumor cells although further investigation needed." (PMID 40926176, 2026). "Furthermore, analysis of tumor cells in the GSE149614 dataset revealed that “don't eat me” ligands CD47, CD24, human leukocyte antigen A (HLA‐A), and HLA‐B were significantly upregulated in tumor cells from NUPR1‐high samples, indicating a potential effect of NUPR1+ macrophages on tumor cells." (PMID 40305758, 2025). "(2021) reported that an anti‐CD47 monoclonal antibody combined with the STING agonist cGAMP (intratumourally administrated) could efficiently enhance the systemic antitumour immune response, prevent tumour metastasis and partially cure tumour‐bearing mice, which is consistent with our results." (PMID 40240911, 2025). "However, a relatively uniform minimum of 80% CD47 repression achieved through CRISPR interference (CRISPRi), combined with the ineffective monoclonal antibody (anti-Tyrp1), enables phagocytosis to dominate net growth, triggering an effective anti-tumor immune response." (PMID 38543240, 2024). "Taken together, m6A‐mediated upregulation of Tug1 is closely related to tumor immunity, and it could inhibit the antitumor immune response of CD8+ T cells by promoting Pdl1 expression, and inhibiting the phagocytosis function of macrophages toward cancer cells by promoting Cd47 expression." (PMID 38981064, 2024). "Notably, this is almost an order of magnitude lower than the concentration typically used for CD47 blocking Abs and recombinant SiRPα-Fc proteins and likely explains the detection of T cell–secreted CV1-Fc but not wtSiRPα-Fc binding to CD47+ tumor cells from culture supernatants." (PMID 38828721, 2024).
tumor (continued). "In addition, it has been reported that CD47/SIRPA blockade with either SIRPα variants acting as an analogue of anti-CD47 antibody or anti-SIRPA antibody does not effectively induce phagocytosis on its own and requires additional tumor-opsonizing antibodies to be efficacious." (PMID 38920727, 2024). "We hypothesize that when patients with heterogeneous tumor cell expression of CD36/47 are treated with VT1021, tumor cells with high CD36 and CD47 would be killed, but tumor cells with low levels of CD36 and CD47 would not respond to the VT1021 treatment, resulting in a lack of response." (PMID 39627379, 2024). "Therefore, a comparison of CD47 expression in relation to the pathological tumor stage could not be made between these two groups." (PMID 39795582, 2024). "However, the lack of CD47 regulation deteriorated the long-term anti-tumor efficacy of macrophages." (PMID 37951973, 2023). "In addition to CD47, the macrophage surface leukocyte immunoglobulin-like receptor B1(LILRB1) protein can specifically recognize major histocompatibility complex I(MHC I) and microglobulin-like β2 (β2M) on the surface of tumor cells, allowing tumor cells to directly escape macrophage phagocytosis." (PMID 36911723, 2023). "Additionally, the inhibition of CD47, a ligand for the macrophage-associated signal-regulatory protein α (SIRPα) has been shown to increase phagocytosis of EC tumor cells by TAMs, although CD47- SIRPα pathway inhibition has not yet been considered for clinical trial." (PMID 36072799, 2022). "Anti-CD47 clone STI-6643 was affinity-engineered to exhibit reduced binding affinity towards its target with the hypothesis that avidity rather than affinity would drive target engagement and thus it would lower on-target off-tumor toxicity and improve bioavailability." (PMID 35664753, 2022). "Furthermore, previous studies have shown that CD47-lentiviruses are more effective in transducing SIRPα+ non-phagocytic tumor cells, suggesting that the interaction of CD47 with SIRPα may facilitate lentiviral engulfment by target cells." (PMID 36454036, 2022). "In addition, published work indicated that an anti-CD47/PD-L1 dual-targeting fusion protein IAB could restore the host’s immune response in vivo by activating both innate and adaptive immunity for more effective tumor eradication." (PMID 36009390, 2022). "Therefore, aCD47/PB-Gel could not effectively inhibit the expression of CD47 at the tumor site in the early postoperative stage." (PMID 35832081, 2022). "Targeting CD47 with non-FcR activating agents or directly targeting SIRPα could avoid an important part of the killing of non-tumor cells bearing CD47 while preserving the tumor cytotoxic capacity of PMN." (PMID 35795660, 2022). "Furthermore, therapeutic blockade of TSP1/CD47 signaling using antibodies or antisense CD47 knockdown enhances antigen-dependent killing of irradiated tumor cells by mouse and human CD8+ T cells in vitro and tumors in athymic mice following adoptive transfer of tumor-specific CD8+ T cells." (PMID 33925464, 2021). "In addition, the Fc portion of some CD47 antibody could also drive macrophage for the antibody-dependent cellular phagocytosis (ADCP), which could further strengthen the macrophage-mediated anti-tumor activity." (PMID 34675914, 2021). "Notably, a recent study demonstrated that the combination of CD47/SIRPα inhibition with activation of CD40 signaling using a SIRPα-Fc-CD40L fusion protein also enhances type I interferon responses in macrophages, increasing effector T cell activity, further blocking tumor growth." (PMID 33801234, 2021). "The results showed that LSD1 inhibitors combined with anti-mouse CD47/PD-L1 mAb significantly inhibited tumor growth and altered the tumor microenvironment, indicating that LSD1 may contribute to tumor immune escape through the suppression of immune surveillance against tumor cells." (PMID 33731702, 2021).
tumor (continued). "Studies showed that some CTCs can upregulate the expression of CD47 on their surface, which is identified by SIRPα (also known as macrophage fusion receptor) on the surface of macrophages and DCs, then transmitting the ‘do not eat me’ signal and inhibiting the clearance of tumor cells." (PMID 31980023, 2020). "Due to the commonly seen increased expression of CD47 in cancer cells, in the last decade, an increasing number of scientists have postulated CD47 as a prognostic factor in several types of tumors; however, evidence of the usefulness of CD47 as a biomarker has not been conclusive for every tumor." (PMID 33015199, 2020). "However, one advantage of anti-CD47 is that a main treatment effect is macrophage/microglia-mediated phagocytosis of tumor cells, which may not be altered by TMZ therapy." (PMID 31547758, 2020). "However, it is not clear how CD47 blockade facilitates tumor immunosurveillance." (PMID 31544856, 2018). "Furthermore, mice harboring inactivating mutations at the SIRPα cytoplasmic tail show similar growth and metastasis of implanted syngeneic melanoma tumor cells as wild-type mice, suggesting again that disruption of CD47-SIRPα alone does not yield an effective antitumor response." (PMID 29387053, 2017). "To determine whether enhanced tumor growth and reduced tumor necrosis formation in mice lacking CD47 were due to greater angiogenic potential of CD47-deficient endothelial cells, we next measured the microvessel density (MVD) by CD31 staining in tumor tissues from WT and CD47-deficient mice." (PMID 27283989, 2017). "Furthermore, we did not detect any direct cytotoxicity of CD47 siRNA on NSCLC cells by MTT assay, suggesting that benefits from CD47 siRNA at least in vitro was not due to the direct toxicity on tumor cells, but rather from the inhibition of cell migration/invasion." (PMID 27411490, 2016). "Given that CD47 expression levels were not greatly different across most tumor lines, we believe that donor-related Sirp expression-levels may have partially contributed to the range of baseline- and induced-phagocytosis strength toward GBM samples within macrophage subtypes." (PMID 27092773, 2016). "Therefore, direct targeting of SIRPα in immune cells, rather than CD47 in tumor cells, could be considered as an alternative approach to disrupt their interaction." (PMID 27671753, 2016). "However, recent studies suggest that macrophages may play an important role, as resident macrophages can eliminate the invading tumor cells if they do not express adequate levels of the CD47 molecule." (PMID 26674012, 2015). "hIgG was detected only in the tumor tissue but not the tumor-draining lymph node (tdLN) and serum, suggesting localized expression of NDV vectorized CD47-blocking agents (andS3)." (PMID 41322194, 2025). "Tumor conditioning upregulates macrophage CD163, CD206, CD80, and LILRB1 without impairing phagocytosis; CD47 blockade similarly enhances A2780 cell clearance in conditioned and control macrophages." (PMID 41280929, 2025). "(2024) developed non-cleavable CD47-targeting ADCs (7DC2-DM1, 7DC4-DM1) showing near-complete tumor inhibition in CRC and lung cancer models with improved safety versus cleavable constructs." (PMID 41256852, 2025). "Ultimately, we found that ECGs presented different profiles across 20 cancer types, with CD47 and TYRO3 more frequently exhibiting copy number increases rather than losses in the majority of tumours, while AXL and HAVCR1 showed a relatively opposite trend." (PMID 40576208, 2025). "Lack of sufficient tumor tissue from the clinical trial precluded correlation of baseline PD-L1, EGFR, and CD47 expression with response, and precluded posttreatment assessments." (PMID 41171165, 2025). "pCAR-NPs work in situ on the “local” macrophage surrounding the postoperative tumor cavity, producing CAR-M there that targets the removal of glioma stem cells (GSCs); in the meantime, CD47 antibodies prevent tumors from sending the “do not eat me” signal." (PMID 40230883, 2025).
tumor (continued). "Unlike CD47, CD24 has a more restricted distribution in healthy tissues and higher expression in tumor tissues." (PMID 41354057, 2025). "However, “do-not-eat-me” signals may be blocked by inhibiting CD47 on tumor cells." (PMID 40422244, 2025). "These CAR-Ms have predominantly targeted a variety of canonical tumor antigens including, but not limited to, CD19, CD47, HER2, and EGFRvIII." (PMID 40082557, 2025). "Studies are also needed to determine the extent to which CD47 and IFT57 are coregulated in nonmalignant cells in the tumor microenvironment." (PMID 39201643, 2024). "The interaction of CD47 and signal regulatory protein (SIRP) α provides a “do not eat me” signal to inhibit tumor phagocytosis by macrophages, and thus, antibodies against CD47 or SIRP have been developed for reserving immunosuppression." (PMID 39204373, 2024). "When the combination of CD47-directed immunotherapy with MTX-based chemotherapy was studied on AT3 cancers, no additive interaction of these drugs resulting in tumor growth blockade was observed." (PMID 38892394, 2024). "Positive correlations between CD47 expression and B cells, CD8+T cells, macrophages were found, while negative correlation among CD47 expression and tumor purity were found." (PMID 37719086, 2023). "IHC analyses of tumor tissues showed that afatinib, but not the anti‐CD47 antibody, treatment reduced the levels of EGFR p1068, c‐Src pY416, and CD47 expression." (PMID 37541303, 2023). "Targeting the “do not eat me” signals CD47 and CD24 with an antibody or Fc-fusion proteins increases the macrophage phagocytosis of tumor cells and enhances antitumor immunity." (PMID 38016957, 2023). "This was associated with transcriptome alterations, indicating that the absence of CD47 leads to increased exhaustion of NK cells and CD8 T cells in tumor-bearing cd47−/− mice." (PMID 36768931, 2023). "Since platelets and erythrocytes also exhibit CD47, the Sendai virus and anti-CD47 were packaged in PLGA nanoparticles for superior accumulation in the tumour microenvironment and to reduce non-specific disruption of the normal blood cells and platelets." (PMID 36851335, 2023). "An increase in CD8+ T cells number per gram of tumor in the current study supports the survival benefit and the decrease in tumor size results, except we did not observed the benefit in the survival of mice receiving OXP and anti-CD47." (PMID 36774400, 2023). "For this, we cultured GBM explants in perfusion bioreactors and treated with anti-CD47, anti-PD1, or their combination which induced an IFN-γ response only in the tumor center, but not periphery." (PMID 38127790, 2023). "A combination of NP-pCAR and anti-CD47 boosts the immune system response against tumor cells and enhances memory T cells and TILs recruitment in the TME, inhibiting tumor relapse without significant toxicity." (PMID 38017494, 2023). "Consistently, our data also showed that anti-CD47 antibodies (including BC31M4, BC31M5 and Hu5F9) monotherapy did not confer antitumor activity in the syngeneic mouse tumor models although they conferred potent antitumor activity in xenograft models." (PMID 36650558, 2023). "Therefore, targeting CD47 alone may not be sufficient for a durable anti-tumor response." (PMID 38188674, 2023). "Even when the CD47-SIRPα axis was disrupted using anti-CD47 Fab fragments, neutrophil-mediated ADCC was not improved, although tumor cell elimination was significantly increased when combined with sodium stibogluconate (SSG; an alleged inhibitor of SHP-1)." (PMID 35884427, 2022). "As a new SIRPα-Fc fusion protein targeting the CD47/SIRPα pathway, IMM01 exhibited strong dual-functional anti-tumor activity through phagocytosis by blocking the “do not eat me” signal and activating the “eat me” signal." (PMID 36080360, 2022). "Hyperactivated CD47/SIRPα and PD1/PD‐L1 signals in CD68+ TAMs in tumor tissues are negative prognostic markers for ICCs after resection." (PMID 35317832, 2022).
tumor (continued). "When evaluating the CD47 expression, our data showed that CD47 expression in TIIC is relatively high, but does not differ statistically from CD47 expression in tumor cells (data not shown)." (PMID 36171566, 2022). "Furthermore, HLA class I deficient B6-F10 tumor growth has been reported to be suppressed in immunodeficient non-obese diabetic (NOD)-scid IL2Rgammanull mice, although LILRB2 gene deficiency did not enhance CD47 disruption-mediated cancer cell phagocytosis in vitro." (PMID 34638388, 2021). "Among the tumor cell clusters identified, two separately clustered categories of cells were observed: tumor cells expressing EpCAM, FOLR1, or both, with high expression of CD47 and those without high expression of CD47 (total clusters n = 10)." (PMID 33670410, 2021). "This was found to correlate with elevated TAM quantities, and it was presumed that increased tumour clearance was achieved by turning TAM-related “eat me” signals on (doxorubicin) and “do not eat me” signals off (CD47 mAb)." (PMID 32961800, 2020). "While no single tumor model can fully recapitulate the pathogenesis and progression of malignancy in humans, consistent findings from a wide variety of different types of mouse models could ultimately lead to the development of novel CD47-targeting treatments for cancer patients." (PMID 32082311, 2020). "As shown, the tumor- and adjacent tissue-infiltrating NK cells and CD8+ T cells exhibited significantly higher staining intensity with the CD47-specific antibody than the nonlymphocyte population." (PMID 32811852, 2020). "Regardless of this, the levels of CD47 on the surface of the tested NK cells and CD8+ T cells were mostly higher than in the parallel nonlymphocyte cell fraction, which contains tumor cells in the tumoral compartment." (PMID 32811852, 2020). "Therefore, CD47 blockage represents a promising avenue to create pro-inflammation TME that could augment anti-tumor response by enhancing M1 macrophage response which may be particularly effective for GBM treatment considering the surprisingly high composition of TAMs, 30–50% of tumor mass." (PMID 32824974, 2020). "Using syngeneic mouse models implanted with PDAC cells, we observed that CD47 blockade alone inhibited tumor growth in the Panc02, but not MPC-83 syngeneic mouse model, though in both models, there were increased tumor-infiltrating PD-1+CD8+ T cells." (PMID 31771616, 2019). "Tumor cell mitoses, CD68+ or CD163+ macrophages, CD47, calreticulin, or checkpoint molecules were not significantly different in these two groups." (PMID 30938231, 2019). "Our flow cytometry data revealed that combination treatment with anti-CD47 and anti-PD-L1 increased the levels of tumor PD-1+CD8+ T cells infiltrate and decreased the tumor burden in the MPC-83 but not in the Panc02 syngeneic mouse model." (PMID 31771616, 2019). "The inactivation of MYC in tumor models results in recruitment of immune cells promoting tumor regression; conversely, the constitutive expression of CD47 and PD-L1 in MYC T-ALL mouse prevented tumor regression even in the absence of MYC." (PMID 29783691, 2018). "TAM repolarization is apparently independent of which arm of the CD47-SIRPα interaction is targeted, as this phenotype was also described for mice treated with an antibody against SIRPα in a RENCA tumor model." (PMID 30133535, 2018). "Importantly, anti‐CD47, which blocks the CD47‐SIRPα inhibitory signaling axis on RBCs, selectively impaired RBC‐exosome uptake (P < 0.05) without affecting tumor‐exosome attachment and internalization." (PMID 41159542, 2026). "Additionally, our analysis of public single-cell sequencing data revealed that C1qbp-positive TAMs exhibit more immunosuppressive interactions with tumor cells compared to C1qbp-negative TAMs in TNBC patients, including CD47-SIRPα." (PMID 38773982, 2024).